BAX (BCL2 associated X, apoptosis regulator)
Diseases named in the same sentence as BAX in open-access papers (continued):
Sharing a sentence is not in itself a finding about the gene and the disease.
cancer (continued). "Western blot analysis revealed a marked increase in BAX and PARP1 expression in cancer cells treated with anlotinib alone or in combination with DDP, accompanied by a decrease in BCL2 expression." (PMID 39508048, 2024). "K-means clustering of >600 000 cancer cells and cell level intensities of APAF1, procaspase-9, procaspase-3, XIAP, SMAC, BAX, BAK, BCL2, BCL-XL, MCL-1, procaspase-8, BID, FADD, FLIP, RIP3 and CIAP1 identified distinct cell cluster profiles." (PMID 39886119, 2024). "A current report has revealed that normal expression of BAX in tumor cells was related with better consequences, while expression of BCL-2 in cancer cells affected drug resistance." (PMID 38287318, 2024). "In contrast, a few individual genes, such as BAX, CLAR, HMGB1, HSP90A11, IFNA1, and PDIA3, showed weak correlations with the ICD scores in most cancer types." (PMID 38627900, 2024). "In cancer cells, BCL-2 is usually upregulated, inhibiting the proapoptotic BAX; therefore, inhibiting apoptosis." (PMID 38246945, 2024). "BECLIN-1, through the interaction with BCL-2 protein, also promotes the release of pro-apoptotic molecules, like BAX and BAK in some type of cancer cells." (PMID 39555455, 2024). "Recent studies have shown that co-targeting BAX and BCL-XL proteins can overcome cancer resistance to apoptosis." (PMID 38988712, 2024). "XPO5 mutations subsequently disrupt its role as a tumor suppressor gene and modulator for cancer through attenuated production of miRNAs that, in turn, promote growth regulatory gene TGGBR2 as well as proapoptotic gene BAX." (PMID 37373948, 2023). "Cancer cells inhibit the mitochondrial apoptosis pathway by upregulation of pro-survival BCL-2 proteins, which results in bound BAX and BAK proteins and inhibition of cellular apoptosis." (PMID 36795726, 2023). "Apoptosis is crucial in preventing cancer development and is mediated by proteins such as BCL-2 and BAX, which leads to rapid cell death with unique biochemical and morphological characteristics." (PMID 37047788, 2023). "RAC1, BAX, EEF1E1, and LPCAT1, four highly interacted genes, showed differential expression at gene levels in HCC and played essential roles in cancer cells." (PMID 37999208, 2023). "Obatoclax was developed as a pan-BH3 mimetic to induce apoptosis of cancer cells by disrupting multiple interactions, including those between anti-apoptotic BCL2 family proteins (BCL2, BCLXL, and MCL1) and BAX and BAK interactions." (PMID 37759469, 2023). "Bcl2 family of interacting proteins play a pro‐survival role whereas family members BAX and Bcl‐2 homologus antagonist/killer (BAK) play an opposing role in the regulation of apoptosis in cancer, cardiomyocyte, and muscle cells." (PMID 36945866, 2023). "It has been well documented that chemoresistance is induced by the inhibition of pro-apoptotic proteins such as PTEN, BAX and Bad and the overexpression of anti-apoptotic proteins such as p-AKT, survivin, XIAP, Bcl-2 and Bcl-xL in resistant cancer cells." (PMID 35456022, 2022).
cancer (continued). "Our findings provide insights into apoptotic resistance mechanisms and investigate the combination of direct BAX activation and BCL-XL inhibition as a novel therapeutic strategy that can broadly overcome apoptotic resistance in cancer." (PMID 35256598, 2022). "Our results demonstrate the role of GAS5 as a ceRNA of miR-128-3p in 5-FU resistance by promoting BAX-inducing cell death and suggest a potential use of GAS5 for effective chemotherapy to improve the efficacy of anti-cancer drugs." (PMID 36672566, 2022). "Our work identified functional assays and markers to predict sensitivity on concurrent BAX activation and BCL-XL inhibition, based on the BAX:BCL-XL complexes and BH3-profiling of cancer cells." (PMID 35256598, 2022). "Bifidobacterium can promote the expression of the proapoptotic gene BAX in CRC, reduce the expression of Bcl-2, and promote apoptosis of cancer cells." (PMID 35992678, 2022). "BAX/BCL-2 ratio is among the most widely studied and reported protein expression pattern for assessment of apoptotic cancer cell death aimed to determine the eventual outcome, leading to apoptosis or survival." (PMID 35408514, 2022). "According to research findings, the balance of pro-apoptotic and anti-apoptotic proteins, including the BAX and BCL2, is effective in cancer cell growth." (PMID 35463725, 2022). "In cancer cells, tricistronic expression of MOAP1, BAX, and RASSF1A (MBR) expression will induce cell death and thus increase chemo-sensitization." (PMID 35269511, 2022). "Previous reports have shown that IM induced an increase in caspase 3 and 7 expression, BAX, and cytochrome C and TUNEL-positive marking, in cardiomyocytes and cancer cell lines." (PMID 36233113, 2022). "BAX and SMAC are often dysregulated in diseases such as cancer or neurodegeneration and are two key regulators that interact with the caspase system generating the apoptotic switch." (PMID 33558564, 2021). "As there was an increase in the proliferation in cancer cells and mammospheres after fractionated irradiation, we further assessed apoptosis and the expression of anti- and proapoptotic genes, BCL2 and BAX." (PMID 33419140, 2021). "Mounting evidence indicates that gene targets in MSI-H cancer include a growing list of cancer genes, including TGF-β1 gene and BAX gene." (PMID 34257589, 2021). "Though its role in inhibition of mitochondrial BAX/BAD pathway is well known, our finding is the first to clarify the critical role of mitochondrial HK-II in preventing pyroptosis in cancer cells." (PMID 34108030, 2021). "Therefore, blocking the antiapoptotic and poor prognostic marker BCL2 and inducing the exogenous expression of the pro-apoptotic and favorable prognostic marker BAX in cancer tissues, could be considered in the development of antioncogenic therapies strategies." (PMID 34946681, 2021). "PI3K/AKT/mTOR inhibition via various molecules or compounds have been shown to induce cancer cell apoptosis through reduction of mitochondrial membrane potential, inactivation of XIAP, activation of caspase-3, upregulation of BAX and downregulation of Bcl-2." (PMID 32443471, 2020). "During the experiment, the expression of the proapoptotic BAX gene and antiapoptotic BCL2 gene in ovarian OV7 cancer cells treated with CAPE were evaluated." (PMID 32752091, 2020). "MCL1 impedes BAK/BAX-dependent apoptosis, and S63845 inhibits the binding of BAK and BAX to MCL1, resulting in cancer cell death." (PMID 32152266, 2020).
cancer (continued). "The effect of BAX and BAK deletion on the expression levels of other genes related to cancer drug resistance were analyzed by Human Cancer Drug Resistance RT2 ProfilerTM PCR array assay with DLD-1 cellular models." (PMID 31551763, 2019). "CircAMOTL1 overexpression in cancer cells remarkably increased anti-apoptotic gene BCL2 expression and inhibited pro-apoptotic gene BAX and BAK expression." (PMID 31819016, 2019). "Re-introduction of MOAP1 induced the expression of apoptotic proteins BAX and cleaved caspase 3 in miR-92a-3p expressing CRC cells, thus promoting cancer cell apoptosis." (PMID 31064356, 2019). "These anti-apoptotic proteins are highly expressed in many cancers and inhibitors known as BH3 mimetics have been designed to target them in order to displace the BH3-only proteins, activate BAX and BAK, thereby inducing MOMP and apoptosis of cancer cells." (PMID 31341643, 2019). "The pro-apoptotic proteins BAX and BAK are important to the induction of apoptosis in cancer cells via the interaction with mitochondrial voltage-dependent anion channels and induction of downstream cytochrome c release." (PMID 31551763, 2019). "In cancer cells, in addition to PUMA and BAX, PpIX induced the expression of heme oxygenase HMOX-1, a stress response gene." (PMID 30886745, 2019). "Of the BAX/BAK-like BCL-2 protein subfamily, the role of BOK is just recently being explored in the context of human cancers." (PMID 29374142, 2018). "BAX and BAK are pro-apoptotic proteins whose activity is essential for the action of many anti-cancer drugs and to suppress tumorigenesis." (PMID 30478310, 2018). "In unstressed cancer cells TRIM28 represses the expression of pro-apoptotic genes: TP53AIP1, BAX, BBC3 (PUMA) and PMAIP1 (NOXA), further suggesting that TRIM28 provides survival advantage to cancer cells." (PMID 28851455, 2017). "More specifically, BAX exerts pro-apoptotic activity while BCL-2 is an anti-apoptotic protein that inhibits apoptosis and is overexpressed in cancer." (PMID 29340085, 2017). "The mechanistic action of current BH3 mimetics for cancer therapy is designed to block the binding between BCL2 and BIM, BAX and BAK." (PMID 27049723, 2016). "BAX protein was strongly activated by IFN-β treatment when compared to 5-FU anti-drug treated cells, but a synergistic effect of cytokine and anti-cancer drug was observed in the co-treatment group." (PMID 26716512, 2016). "On the other hand, due to genomic deletion or promoter methylation leading to transcriptional silencing, loss-of-function of several pro-apoptotic proteins such as BAK, BAX and BH3-only family members have been observed in a variety of cancer types." (PMID 27455839, 2016).
cancer (continued). "Previous studies have noted that melatonin alters the balance between BAX and BCL-2 in some cancer cells by up-regulating BAX expression, resulting in MOMP and cytochrome c release." (PMID 26025920, 2015). "Anti-apoptotic members of the family (such as BCL-2, BCL-XL, BCL-W and MCL-1), which are overexpressed in many cancers, function by sequestering the pro-apoptotic executioners of the MOMP (such as BAX and BAK)." (PMID 26230693, 2015). "Recently, the let-7 family as well as miR-886-5p were shown to regulate apoptosis of cancer cells by targeting BCL2L1 and BAX, respectively." (PMID 21629653, 2011). "To further study the possible mechanisms involved in GRP78-mediated cancer stemness properties, we found out knockdown of GRP78 enhanced the expression of PTEN, BAX and Caspase3 but reduced the expression of p-MAPK in HN-CICs." (PMID 20979610, 2010). "These two cases presented also alterations in the BAX and IGF2R genes in their carcinomas, which are compatible with a constitutional MMR deficiency that leads to an acquired genetic instability." (PMID 20979647, 2010). "EP300, ISGF3G, STAT1, and STAT3 are up regulated in 8/13 of cancer models, while ATM, BAX, BCL2L11, HTATIP2, LGALS3, MAPK1, and TP73L are down regulated in half of cancer models." (PMID 19402918, 2009). "In addition, fisetin significantly modulated the level of cancer-related genes such as those involved in the PI3K/AKT/mTOR pathway, apoptotic genes, BAX and BCL-2, and the transcription factor gene NF-κB." (PMID 41180483, 2025). "The upregulation in BAX expression, but downregulation in BCL2 expression in cancer therapies may indicate that cells are directed to apoptosis." (PMID 40576246, 2025). "However, in cancer, as there are variations in the levels of proteins and enzymes related to apoptosis, including BAX, BCL-2 and Caspase-3 on the apoptotic pathway, apoptosis is inactivated and the rapid progression of cancer continues." (PMID 41614842, 2025). "Furthermore, elevated expression of BAX and a concomitant reduction in BCL‐2 were observed in the combination treatment group, suggesting an augmentation of cancer cell apoptosis through this combinatorial approach." (PMID 41020311, 2025). "In a large-scale RNAi screening aimed at understanding cancer dependencies and synthetic lethal relationships, the top correlates of WSB2 co-essentiality were found to be MCL-1, BCL-2, and MARCH5, while the most strongly anti-correlated gene with WSB2 was BAX." (PMID 40699886, 2025). "BAX (pro‐apoptotic) and BCL2 (anti‐apoptotic), members of the mitochondrial apoptotic pathway, are regulated during carcinogenesis and prevent the death of cancer cells." (PMID 40576246, 2025). "This study demonstrates that carvacrol exerts multi-targeted anticancer effects in both HR+ (MCF-7) and TNBC (MDA-MB-231) BC cells by enhancing the BAX/BCL2 ratio, inducing apoptosis, reducing oxidative stress, and downregulating CD44+ cancer stem cell marker levels." (PMID 41154846, 2025). "Our findings that FN combined with anticancer drugs further upregulated the BAX/BCL-2 and cleaved caspase-9/caspase-9 ratios relative to drug treatment alone support the hypothesis that FN sensitizes cancer cells to apoptosis." (PMID 41614757, 2025). "Cancer cells prevent apoptosis through modulation of Bcl-2 proteins, via upregulation of anti-apoptotic and pro-survival proteins, such as BCL-2, BCL-XL, and MCL1, or/and downregulation of pro-apoptotic proteins, such as BAX, BAK, and BOK." (PMID 39860065, 2025). "A Spearman correlation between BAX CNV and mRNA was also explored in pan-cancer." (PMID 39074253, 2024). "As far as the working mechanism of the plant extract for anti-cancer activity, researchers demonstrated that plant extract induced apoptosis in cancer cells by the activation of FOXO3 responsible for the up-regulation of pro-apoptotic BIM and BAX, as well as cell cycle inhibitors." (PMID 39334758, 2024).
cancer (continued). "While, DTX has shown to regulate BAX/BCL-2 ratio instead only suppressing the BCL-2 expression in a dose and time-dependent manner, miR-34a is well reported to downregulate the BCL-2 translation in cancer as well as neurodegenerative diseases." (PMID 39289425, 2024). "Also significantly raises the rate at which cancer cells express BCL-2, BAX, caspases, and the PI3K-AKT-mTOR signaling pathway." (PMID 39605919, 2024). "Resveratrol modulates BAX and BCL-2, critical apoptosis regulators, impacting cancer cell survival." (PMID 39769099, 2024). "Moreover, CuONPs inhibited cell growth and induced apoptosis in various cancer cells by regulating the expression of BCL-2, BAX, and CCND1." (PMID 38813193, 2024). "Therefore, this is the first research on BAX rs704243, NOXA (PMAIP1) rs78800940 and rs1041978 SNPs in HNC or any cancer." (PMID 39519400, 2024). "In UCEC, the same infiltration pattern was observed among samples harboring mutations of genes regulating DNA damage repair and cell cycle but not in patients with mutations of classical cancer hallmarks such as PTEN, MYC, KRAS, BAX and ect." (PMID 37917664, 2023). "Moreover, it exerts a regulatory effect on apoptosis within cancer cells through the modulation of the expression and activity of key apoptotic proteins such as BCL-2, BAX, and cleaved caspase." (PMID 38003971, 2023). "Molecular analysis showed that the pro-apoptotic BAX gene was overexpressed in non-cancer cell lines treated with moxifloxacin and ofloxacin and in cancer cell lines treated with moxifloxacin." (PMID 37534254, 2023). "In addition, flavonoids can exert an effect on the expression, as well as on the activity of apoptotic proteins such as BCL-2, BAX, and cleaved caspase-3 (CASP3), which ultimately leads to the induction of apoptosis in cancer cells." (PMID 37446564, 2023). "In two kinds of GC cells, the interference expression of OIP5-AS1/CD147/TRPM7 could induce the apoptosis of cancer cells by down-regulating the expression of BCL-2 and up-regulating the expression of Caspase3, Caspase9 and BAX." (PMID 38156103, 2023). "Mechanistic anti-cancer assays were performed on Compound 2, revealing noteworthy changes such as MMP reduction, increase in ROS production, inhibition of anti-apoptotic protein BCL-2, and activation of BAX and caspase-3." (PMID 38188932, 2023). "In addition, in human osteosarcoma (U2-OS) and human breast cancer (MCF7) cells, USP30 regulates the BAX/BAK-dependent apoptosis and its deletion sensitizes cancer cells to BH3-mimetics which can promote cell apoptosis." (PMID 35308234, 2022). "Additionally, it increased the expression of BAX and CASP3, and decreased the expression of the anti‐apoptotic gene of BCL‐2 in cancer cells." (PMID 36514755, 2022).